Y_RNA (Y RNA )
Gene: Miscellaneous RNA gene on chromosome 6 (67,625,356 to 67,625,464, forward strand). Ensembl gene ENSG00000206672.
Homologues: Orthologues: chimpanzee Y_RNA (98% identical). Paralogues in human: Y_RNA (83% identical), RNY1P5 (82% identical), Y_RNA (81% identical), Y_RNA (80% identical), RNY1 (79% identical), Y_RNA (79% identical), Y_RNA (78% identical), Y_RNA (77% identical), Y_RNA (76% identical), Y_RNA (75% identical), RNY1P1 (74% identical), RNY1P16 (74% identical), and 92 more.